IQGAP1 (IQ motif containing GTPase activating protein 1)
Diseases named in the same sentence as IQGAP1 in open-access papers (continued):
Sharing a sentence is not in itself a finding about the gene and the disease.
ischemia (1 paper, 2010). A hypoperfusion of the BLOOD through an organ or tissue caused by a PATHOLOGIC CONSTRICTION or obstruction of its BLOOD VESSELS, or an absence of BLOOD CIRCULATION. "Western analysis showed that IQGAP1 protein expression was increased in ischemic muscles at days 3 and 7 after hindlimb ischemia." (PMID 20976168, 2010). "We next examined if the levels of endogenous IQGAP1 are regulated after hindlimb ischemia in vivo." (PMID 20976168, 2010). "Thus, endogenous IQGAP1 plays an important role in ischemia-induced revascularization by regulating macrophage infiltration and EC-mediated angiogenesis." (PMID 20976168, 2010). "Here we provide compelling evidence that ischemia-induced increases in CD31+ capillary-like ECs (angiogenesis) and α-SMA+ arterioles (pericyte recruitment) are significantly reduced in IQGAP1−/− mice, thereby inhibiting blood flow recovery at days 7 and 14 after ischemia." (PMID 20976168, 2010). "However, a role of endogenous IQGAP1 in ischemia-induced neovascularization was virtually unexplored." (PMID 20976168, 2010).
liver diseases (1 paper, 2019). "Studies of different liver diseases, including tumorigenesis, indicate that elevated BA levels induce YAP activation through the IQGAP1." (PMID 31847428, 2019).
malignant glioma (1 paper, 2016). A grade III or grade IV glioma arising from the central nervous system. "In summary, our studies demonstrate that activated Cdc42 is a critical determinant of the migratory and invasive phenotype of malignant gliomas, and that its effect may be mediated, at least in part, through its interaction with IQGAP1 and phosphorylated FAK." (PMID 27486972, 2016). "Our studies demonstrate an interaction of activated Cdc42 with IQGAP1 and phosphorylated focal adhesion kinase (FAK) – an interaction which may contribute to the increased aggressiveness of and invasiveness of malignant gliomas." (PMID 27486972, 2016).
meningitis (1 paper, 2017). A disorder characterized by acute inflammation of the meninges of the brain and/or spinal cord. "In summary, we have identified IQGAP1 as a key mediator implicated in the pathogenesis of E. coli-induced meningitis." (PMID 28469997, 2017). "The fact that U0126 could abolish the stimulating effect of IQGAP1 upregulation on the inflammatory response of the infected brain tissues lent further experimental credence to the involvement of the MAPK pathway in Hcp1-promoted E. coli meningitis." (PMID 28469997, 2017).
metabolic syndrome (1 paper, 2025). A cluster of metabolic risk factors for CARDIOVASCULAR DISEASES and TYPE 2 DIABETES MELLITUS. "This review synthesizes advances in IQGAP1’s structural domains, disease-specific signaling networks, and therapeutic targeting strategies, emphasizing its translational potential in developing precision therapies for cancer, metabolic syndromes, and immune disorders." (PMID 41035668, 2025).
morphine dependence (1 paper, 2022). Strong dependence, both physiological and emotional, upon morphine. "Therefore, the first aim of this experiment was to explore whether miR-124 and IQGAP1 are susceptibility markers of morphine dependence." (PMID 35401251, 2022). "In the multiple regression model, the levels of miR-124 and IQGAP1 were independent factors influencing the severity of morphine dependence." (PMID 35401251, 2022). "MiR-124 and its target protein IQGAP1 are involved in the regulation of addiction and cognitive function in patients with morphine dependence." (PMID 35401251, 2022). "In this study, the OASI score is correlated with miR-124, IQGAP1, and morphine intake in the past year, and the levels of miR-124 and IQGAP1 are independent factors influencing the severity of morphine dependence in morphine-dependent patients." (PMID 35401251, 2022). "Overall, these results demonstrated that miR-124 and its target protein IQGAP1 are involved in regulating cognitive function in patients with morphine dependence." (PMID 35401251, 2022). "Based on previous studies, we hypothesized that IQGAP1, as a direct target of miR-124, may be involved in regulating the addiction and cognitive function of patients with morphine dependence." (PMID 35401251, 2022).
oral squamous cell carcinoma (1 paper, 2021). "Interestingly, a missense mutation in IQGAP1, S459L, was identified in a family predisposed to oral squamous cell carcinoma (OSCC) and this variant was found to be more active than wild-type IQGAP1 in tissue cultures, based upon monitoring levels of MAPK and PI3K signaling." (PMID 34439095, 2021).
osteoporosis (1 paper, 2025). A condition of reduced bone mass, with decreased cortical thickness and a decrease in the number and size of the trabeculae of cancellous bone (but normal chemical composition), resulting in increased fracture incidence. "Disruptions in IQGAP1 function result in abnormal bone turnover, providing a novel perspective on how metabolic dysregulation can contribute to bone fragility and osteoporosis." (PMID 41035668, 2025).
pancreatic adenocarcinoma (1 paper, 2023). "However, we found two GEO pancreatic adenocarcinoma datasets (GSE15471 and GSE16515) in which the KSR1 and IQGAP1 transcripts were down-regulated and up-regulated when compared to healthy tissue control, respectively." (PMID 36791195, 2023).
peritonitis (1 paper, 2010). Inflammation of the peritoneum (tissue that lines the abdominal wall and covers most of the organs in the abdomen). "The present study also shows that ROS production in ischemic muscle, as well as “activated and tissue infiltrated” macrophage obtained by peritonitis inflammation model, is inhibited in IQGAP1−/− mice." (PMID 20976168, 2010). "To address further the role of IQGAP1 in recruitment of inflammatory cells, we used a thioglycollate-elicited peritonitis model to induce non-bacterial inflammation." (PMID 20976168, 2010).
restrictive lung disease (1 paper, 2024). "IQGAP1 was involved in collagen gel contraction and enhanced contractility in lung fibroblasts, suggesting that IQGAP1 contributed to restrictive lung disease by regulating the expression and organization of SMA." (PMID 38791282, 2024).
Salmonella Infections (1 paper, 2009). Infections with bacteria of the genus SALMONELLA. "IQGAP1 was specifically co-immunoprecipitated with SseI-cya, confirming that these factors interact during Salmonella infection." (PMID 19956712, 2009).
scleroderma (1 paper, 2024). Scleroderma is a rare autoimmune connective tissue disorder characterized by abnormal hardening of the skin and, sometimes, other organs. "Previously, we reported that IQGAP1 was elevated in lung fibroblasts isolated from scleroderma (systemic sclerosis, SSc) patients." (PMID 38791282, 2024). "We also found that IQGAP1 expression could be induced in normal lung fibroblasts when exposed to connective tissue growth factor (CTGF, CCN2); moreover, suppression of IQGAP1 by RNA interference decreases the migration of scleroderma and CTGF-induced normal lung fibroblasts." (PMID 38791282, 2024).
type 2 diabetes (1 paper, 2021). "Consistent with our observations in mice, IQGAP1 expression is reduced in adipocytes derived from patients with type 2 diabetes mellitus." (PMID 33191271, 2021).
uterine corpus endometrial carcinoma (1 paper, 2023). A endometrial carcinoma (disease) that involves the body of uterus. "CD2AP had the lowest methylation level in uterine corpus endometrial carcinoma (UCEC), and IQGAP1 had the highest methylation level in UCEC." (PMID 38235128, 2023).
cancer (128 papers, 2008 to 2026). A tumor composed of atypical neoplastic, often pleomorphic cells that invade other tissues. "Beyond its roles in normal cellular physiology, IQGAP1 has been implicated in a range of pathological conditions, including various cancers, immune diseases, metabolic disorders, and cardiovascular conditions." (PMID 41035668, 2025). "This is supported by an increase in the expression of IQGAP1 P < 0.0005, a marker of adherence which is associated with the metastatic competency of cancer cells." (PMID 40434957, 2025). "This analysis revealed that IQGAP1, FLNB, and ACTB are involved in the “Proteoglycans in cancer” pathway, IQGAP1, ABI2, and ACTB are associated with the “Regulation of actin cytoskelet”, IQGAP1 and ACTB are linked to the “Adherens junction”." (PMID 40672380, 2025). "IQGAP1 is a scaffold protein with oncogenic potential, as it is implicated in various functions traditionally associated with cancer, including proliferation, migration, invasion, and cell-cell adhesion." (PMID 38424547, 2024). "In conclusion, the CGN c.3560C > T variant leads to overexpression of IQGAP1 and activation of Rac1, correlating with metastasis and drug resistance in cancer cells." (PMID 38424547, 2024). "This overexpressed IQGAP1 was consistently associated with the activation of Rac1, as evidenced by the analysis of the cancer cell line and clinical sample harboring CGN c.3560C > T." (PMID 38424547, 2024). "IQGAP1 has also been characterized as an oncogene implicated in several types of cancer including pancreatic." (PMID 37635636, 2023). "IQGAP1 is a multidomain cancer-associated protein that serves as a scaffold protein for multiple signaling pathways." (PMID 37145016, 2023). "IQGAP1 is of particular interest as a therapeutic target because it serves as a node for many signalling pathways implicated in cancer progression." (PMID 33473262, 2021). "IQGAP1 is overexpressed in many types of cancer, and its overexpression in cancer is associated with lower survival of the cancer patient." (PMID 34439095, 2021). "We start by describing the major cancer-related signaling pathways scaffolded by IQGAP1 and their associated cellular activities." (PMID 34439095, 2021). "IQGAP1 is involved in a myriad of pathways commonly associated with cancer and metastasis, including proliferation, migration and invasion." (PMID 32051509, 2020). "The scaffold protein IQGAP1 has been an active subject of investigation for its oncogenic potential due to its involvement in multiple functions classically associated with cancer, including proliferation, migration, invasion and cell-cell adhesion." (PMID 32051509, 2020). "Overall, these findings present a novel role for IQGAP1 in modulating the levels of centrosome proteins, failure of which leads to centrosome aberrations associated with cancer." (PMID 32655836, 2020). "While overexpression of IQGAP1 has been implicated in these carcinomas and proposed as clinical target, its mechanism is just emerging." (PMID 32655836, 2020). "Aberrant activity of the IQ-containing GTPase Activating Protein (IQGAP1) associates with many carcinomas, including TNBC." (PMID 32655836, 2020). "The results revealed that the mutation frequencies of both VAV2 and IQGAP1 are higher in HNSCCs than in any other cancer types." (PMID 31798960, 2019). "To determine if the susceptibility genes identified in the OSCC family are associated with HNSCCs, we screened the ICGC dataset and analyzed the mutation frequencies of VAV2 and IQGAP1 in different cancer tissues derived from 19 different anatomic sites." (PMID 31798960, 2019). "Because of this association with molecular partners, IQGAP1 accumulates in the plasma membrane at the invasive front in several cancer types." (PMID 28441737, 2017). "The top ten proteins up-regulated by short-term cholesterol treatment included Ras GTPase-activating-like protein IQGAP1, a protein implicated in tumor metastasis in several cancers." (PMID 25924234, 2015).
cancer (continued). "IQGAPs participate in cancer cell invasion and the overexpression of IQGAP1 is associated with unfavorable prognosis in various cancers." (PMID 23408967, 2013). "Human IQGAP proteins function in cancer cell metastasis, and altered expression of IQGAP1 and IQGAP2 is implicated in tumorigenesis." (PMID 22505937, 2012). "Changes in expression of IQGAP1 have been linked to human cancers, and many IQGAP1 binding partners also have functions in cancer progression." (PMID 22505937, 2012). "Considering that both RhoC and IQGAP1 have role in regulating proliferation of cancer cells and their expressions were highly correlated, we further explored the functional association between RhoC and IQGAP1." (PMID 23145020, 2012). "IQGAP1 has been implicated in the regulation of tumor drug resistance across various cancer types." (PMID 41035668, 2025). "Therefore, the observed interaction between MISP, IQGAP1, and Cdc42 sheds light on potential mechanisms underlying cancer progression, highlighting promising avenues for further investigation and therapeutic intervention." (PMID 38785491, 2024). "Based on the cancer data, we hypothesize that genetic variants in IQGAP1 may result in decreased cell migration." (PMID 37635636, 2023). "Indeed, IQGAP1 has been reported to rise at both the mRNA and protein levels in an assortment of cancers, and its levels have been associated with cancer aggressiveness." (PMID 36276098, 2022). "With a better understanding of the role of IQGAP1 in cancer and the underlying mechanism, therapies targeting IQGAP1 and its related signaling will potentially be beneficial, especially since many cancers overexpress IQGAP1 and/or depend upon IQGAP1-mediated signaling." (PMID 34439095, 2021). "The new insights that have emerged about IQGAP1′s role in tumor-associated immune cells, especially TAMs and T cells, might intensify the efficacy of direct cancer-killing effects and enhance beneficial immune response at the same time." (PMID 34439095, 2021). "Among the possible interacting proteins, IQGAP1 was further studied (Source data 2) because its expression is associated with the aggressiveness of various types of cancer." (PMID 34590580, 2021). "Given the importance of PI3K in HPV-associated cancers, we hypothesized that IQGAP1 also plays a role in PV-associated head and neck tumorigenesis." (PMID 34068608, 2021). "However, loss of IQGAP1 significantly reduced the number of HPV-associated carcinoma foci, specifically in the esophagus, relative to the tongue." (PMID 34068608, 2021). "Given the critical role of IQGAP1 in carcinoma development, anti-tumor therapies targeting IQGAP1 or its associated signaling pathways could be beneficial for patients with many types of cancer." (PMID 34439095, 2021). "The two mechanisms associated with dominant mutants of IQGAP1 appear to exist in cancer cell lines." (PMID 32655836, 2020). "We discuss a model whereby IQGAP1 acts as a signaling scaffold in the centrosome and influences centrosome protein transport, dysfunction of which underlie centrosome aberrations in cancer thereby presenting IQGAP1 as a common target in variants of TNBC, amenable to personalized medicine." (PMID 32655836, 2020). "IQGAP1 has been implicated in the tumorigenesis and progression of several human cancers." (PMID 31101875, 2019). "Since IQGAP1 has been shown to associate with various small GTPases including cdc42 and Rac1, we examined whether or not RalA, previously shown to signal downstream of β-arrestin in cancer cells, can associate with IQGAP1." (PMID 23405264, 2013). "As a scaffold protein, IQGAP1 binds multiple proteins, such as oncogenes β-catenin and Src, tumor suppressor E-cadherin and the Rho GTPases Cdc42 and Rac1, and causes the alteration of cellular behaviors, especially for cancer cells." (PMID 23145020, 2012).
cancer (continued). "Indeed, studies with human IQGAP1, a scaffold protein for multiple cancer-associated signaling pathways, have led to the discovery that its 26-residue WW domain, when engineered as a cell-penetrating peptide, shows broad anti-tumor activity with minimal associated toxicity." (PMID 37145016, 2023). "Overexpression of IQGAP1 enhances the growth and metastasis of HCC, while IQGAP1-deficient cancer cells are more sensitive to apoptosis." (PMID 41035668, 2025). "IQGAP1 regulates small GTPases and is essential for cytoskeletal dynamics, which are crucial for cancer cell motility and metastasis." (PMID 41035668, 2025). "The IQGAP1 protein binds to the estrogen receptor (ER), enhancing its transcriptional activity and promoting cancer cell proliferation." (PMID 41035668, 2025). "IQGAP1 also plays an important role in modulating chemokine receptor signaling, which is vital for cancer cell migration and metastasis." (PMID 41035668, 2025). "This regulation prevents cell death and promotes liver tumorigenesis, emphasizing IQGAP1’s role in promoting cancer cell survival." (PMID 41035668, 2025). "In summary, IQGAP1’s multifaceted roles in cellular regulation, cancer progression, immune modulation, and metabolic disease highlight its potential as a therapeutic target." (PMID 41035668, 2025). "IQGAP1 interacts with MYL9 and acts on the ERK1/2 pathway to regulate cancer-associated fibroblasts (CAFs), which secrete CCL2 and TGF-β1, thereby influencing the tumor microenvironment and patient outcomes." (PMID 41035668, 2025). "IQGAP1 influences cell adhesion and motility through its interactions with integrins and other adhesion receptors, driving cancer metastasis." (PMID 41035668, 2025). "In cancer, IQGAP1 is involved in promoting tumor growth, metastasis, and resistance to chemotherapy and targeted therapies." (PMID 41035668, 2025). "Its deficiency was shown to increase TGFβ signaling in BCa, suggesting that IQGAP1 has the potential to serve as both a clinical biomarker and a cancer growth suppressor." (PMID 40361412, 2025). "The significance of IQGAP1 has expanded beyond its basic cellular roles, revealing its critical involvement in various diseases, particularly cancer, immune disorders, and metabolic diseases." (PMID 41035668, 2025). "The adhesion of cancer cells to endothelial cells requires β1-integrin, and IQGAP1 regulates the transcription and expression of β1-integrin." (PMID 40361412, 2025). "Active Rac1 destabilizes E-cadherin-mediated cell-cell adhesion by interacting with IQGAP1, and inhibiting Rac1 activity induces increased E-cadherin-mediated cellular adhesion in certain cancer cells." (PMID 38424547, 2024). "The overexpression of IQGAP1 and direct interaction with membrane‐bound E‐cadherin was suggested as an essential cellular process for cancer metastasis." (PMID 39073693, 2024). "DSTN and FLNB were downregulated when ACTIN4, INF2, MHY10, FLNA, PDLIM1, and IQGAP1 were upregulated in THCA cancer tissues." (PMID 38584831, 2024). "The existing literature has suggested the potential involvement of IQGAP1 in cancer by modulating signaling pathways pivotal in cell proliferation and transformation." (PMID 38397135, 2024). "(ii) CGN c.3560C > T induces the overexpression of IQGAP1 and activates Rac1 in cancer cells, providing molecular insights into the mechanisms by which this variant influences cellular behavior." (PMID 38424547, 2024). "Because IQGAP1 interacts with so many different proteins, it is important to study how these proteins change over time in cancer." (PMID 38546389, 2024). "AKT and IQGAP1 proteins were highly expressed in the epithelial cancers compared with the non‐cancer tissues (p < 0.05)." (PMID 39073693, 2024). "Our studies further reveal the many facets of IQGAP1’s role in mediating EGF signaling, hence indicating the potential of targeting IQGAP1 for novel anti-cancer therapies that can supplement the existing anti-EGFR chemotherapy." (PMID 39357822, 2024).